MIEF1 (mitochondrial elongation factor 1)
Description:
Mitochondrial outer membrane protein which regulates mitochondrial fission/fusion dynamics. Promotes the recruitment and association of the fission mediator dynamin-related protein 1 (DNM1L) to the mitochondrial surface independently of the mitochondrial fission FIS1 and MFF proteins. Regulates DNM1L GTPase activity and DNM1L oligomerization. Binds ADP and can also bind GDP, although with lower affinity. Does not bind CDP, UDP, ATP, AMP or GTP. Inhibits DNM1L GTPase activity in the absence of bound ADP. Requires ADP to stimulate DNM1L GTPase activity and the assembly of DNM1L into long, oligomeric tubules with a spiral pattern, as opposed to the ring-like DNM1L oligomers observed in the absence of bound ADP. Does not require ADP for its function in recruiting DNM1L. Assembly factor involved in the biogenesis of the mitochondrial-specific ribosomes (mitoribosomes). Specifically associates with intermediates of the mitochondrial ribosome large subunit (mt-LSU) and is required for proper ribosome assembly, possibly preventing premature association of the large and small ribosomal subunits. Thereby, indirectly regulates mitochondrial translation. It is also required for complete assembly of the mitochondrial respiratory chain complex I. May also function in DNM1L-mediated mitochondrial fission.
Synonyms: MID51; SMCR7L; FLJ20232; L0R8F8; D3A; HSU79252; OPA14; dJ1104E15.3
Tractability: Small molecule: a structure with a bound ligand is known. Antibody: UniProt predicts a signal peptide or a membrane-spanning region. PROTAC: ubiquitination databases record sites on it; its protein half-life has been measured.
Gene: Protein-coding gene on chromosome 22 (39,499,432 to 39,518,132, forward strand). Ensembl gene ENSG00000100335.
Subcellular location: Mitochondrion matrix; Mitochondrion outer membrane
Subcellular location (Human Protein Atlas): Intermediate filaments; Mitochondria
Pathways (Reactome):
Metabolism of proteins: Mitochondrial ribosome-associated quality control
Gene Ontology:
Molecular function: ADP binding; GDP binding; identical protein binding; protein binding
Biological process: mitochondrial fission; mitochondrial fusion; positive regulation of mitochondrial fission; positive regulation of mitochondrial fusion; positive regulation of protein targeting to membrane; mitochondrion organization
Cellular component: mitochondrial outer membrane; mitochondrion; mitochondrial matrix; peroxisome
Genetic constraint (gnomAD): Loss-of-function variants: 14 observed, 35.7 expected, observed/expected ratio (o/e) 0.39, 90% interval 0.26 to 0.61. The upper end of that interval is the gene's LOEUF score, 0.61, which puts it in group 2 of 6, group 1 being the genes least tolerant of losing a copy. Missense variants: 542 observed, 644.11 expected, observed/expected ratio (o/e) 0.84, 90% interval 0.78 to 0.9. Synonymous variants: 245 observed, 267.71 expected, observed/expected ratio (o/e) 0.92, 90% interval 0.82 to 1.02.
Homologues: Orthologues: dog MIEF1 (98% identical), rat Mief1 (98% identical), mouse Mief1 (98% identical), guinea pig MIEF1 (98% identical), chimpanzee MIEF1 (94% identical), macaque MIEF1 (94% identical), tropical clawed frog mief1 (74% identical), zebrafish mief1 (71% identical). Paralogues in human: MIEF2 (46% identical).
Diseases named in the same sentence as MIEF1 in open-access papers:
MIEF1 is named in the same sentence as 27 diseases in open-access papers, as found by Europe PMC text mining. Sharing a sentence is not in itself a finding about the gene and the disease. The quoted sentences say what the papers report.
breast carcinoma (5 papers, 2013 to 2026). "Previous research has demonstrated that valproic acid can modulate the compromised mitochondrial function by suppressing the expression of mitochondrial elongation factor 1 (MIEF1), thus inhibiting the proliferation of breast cancer cells." (PMID 40438588, 2025). "However, we found underexpression of EEF2 and GLRX2 proteins involved in ROS; MTX2 in MMO; USP30 in MIT; TSPO in MIT and PPM processes; BAX in FUS; and MTFR1L and MIEF1 in FIS compared to luminal A and basal-like breast cancer tumors." (PMID 35327574, 2022).
autosomal dominant optic atrophies (2 papers, 2022 to 2024). "Mutations in genes associated with mitochondrial fusion, including OPA1, AFG3L2, and MIEF1, lead to autosomal dominant optic atrophies (DOAs), specifically optic atrophy 1 (OPA1), optic atrophy 12 (OPA12), and optic atrophy 14 (OPA14), respectively." (PMID 39201313, 2024).
hepatocellular carcinoma (2 papers, 2022 to 2025). A malignant tumor that arises from hepatocytes. "Immunohistochemical analysis further confirmed that MIEF1 expression was markedly elevated in hepatocellular carcinoma (HCC) tissues compared to normal liver tissues—elevated MIEF1 levels correlated with reduced survival rates in HCC patients." (PMID 40175344, 2025). "To determine whether ASOs can be used to modulate mitochondrial dynamics, we administered a panel of ASOs targeting mitochondrial fusion and fission factors (Mfn1, Mfn2, Drp1, Fis1, Mff, Mief1, Mief2) to MHT (mouse hepatocellular carcinoma) cells in culture." (PMID 34698563, 2022).
colorectal cancer (1 paper, 2022). A primary or metastatic malignant neoplasm that affects the colon or rectum. "Research in colorectal cancer has reported that mitochondrial division is affected by MIEF1." (PMID 35327574, 2022).
diabetes (1 paper, 2019). "We observed that LV expression of Mief1 and USP30 were significantly reduced in diabetic mice, although several other genes assessed (Mief2, Park2 and Park6) were not affected by the presence of diabetes." (PMID 31798462, 2019).
liver cancer (1 paper, 2025). An epithelial or non-epithelial malignant neoplasm that arises from the liver. "Liver cancer patients with a poor prognosis exhibited upregulated expression of MIEF1, and MIEF1 knockdown led to the loss of tumor capabilities, indicating MIEF1 as an oncogene in liver cancer." (PMID 40175344, 2025). "Using loss or gain experiments, we identified Mitochondrial elongation factor 1 (MIEF1) as a critical target of the HELLS molecular network in liver cancer." (PMID 40175344, 2025). "To explore the role of MIEF1 in liver cancer, we analyzed its expression using ICGC data." (PMID 40175344, 2025). "In this study, we identified mitochondrial elongation factor 1 (MIEF1), one of the DRP1 receptors, as a novel oncogene and a direct transcriptional target and critical executor downstream of HELLS in liver cancer." (PMID 40175344, 2025). "Furthermore, overexpression of HELLS increased MIEF1 levels and enhanced colony-forming ability in non-tumorigenic liver cancer." (PMID 40175344, 2025).
lung carcinoma (1 paper, 2022). "YAP-Hippo regulates MIEF1-related mitochondrial stress and activates the JNK pathway to promote the death of A549 lung cancer cells." (PMID 35290415, 2022).
Obesity (1 paper, 2023). Accumulation of substantial excess body fat. "Meanwhile, Mief1 (mitochondrial elongation factor 1), which lies in the dominant Fob2 (Fat line obesity QTL 2) confidence interval identified in our previous study, and Mrpl3 (mitochondrial ribosomal protein L3) encode proteins involved in mitochondrial translation and biogenesis." (PMID 36414820, 2023).
Optic neuropathy (1 paper, 2021). "Together, these results show that MIEF1 mutations linked to optic neuropathy preferentially disrupt the ability of MID51 to regulate mitochondrial fission/fusion dynamics." (PMID 33632269, 2021). "Together, our study identifies dominant MIEF1 mutations as a cause for optic neuropathy and further highlights the important role of properly regulated mitochondrial dynamics in neurodegeneration." (PMID 33632269, 2021). "This was also true for mutant MID51 p.Y240N and p.R146W proteins, which also localized to the mitochondrial network in live cells, demonstrating that these MIEF1 missense variants linked to optic neuropathy do not alter MID51’s mitochondrial localization." (PMID 33632269, 2021). "Thus, these MIEF1 missense variants linked to optic neuropathy do not significantly disrupt the oligomerization of MID51." (PMID 33632269, 2021).
cancer (3 papers, 2022 to 2025). A tumor composed of atypical neoplastic, often pleomorphic cells that invade other tissues. "Moreover, MIEF1 and LY6E may mediate different signalling pathways to induce apoptosis in the corresponding cancer cells." (PMID 35222533, 2022).
neurodegenerative disease (2 papers, 2021). A disorder of the central nervous system characterized by gradual and progressive loss of neural tissue and neurologic function. "In summary, combining our clinical, genetic and pathophysiological data, we identify the first known dominant MIEF1 mutations linked to a human disease, resulting in a specific ophthalmological neurodegenerative disease." (PMID 33632269, 2021). "Together, our work should prompt the molecular screening of MIEF1 in ION individuals with severe alterations of the peripheral visual field, and further emphasizes the crucial role for properly regulated mitochondrial dynamics in neurodegenerative diseases." (PMID 33632269, 2021).
tumor (1 paper, 2025). "In vivo, MIEF1 knockdown significantly reduced tumor size and weight, while the overall body weight of the mouse models remained unchanged." (PMID 40175344, 2025).
MIEF1 also shares sentences with these, for which no sentence is quoted: optic atrophy (3 papers); pulmonary arterial hypertension (3); acute myocardial infarction (1); atherosclerosis (1); Atrophy (1); bone osteosarcoma (1); cardiovascular disease (1); centronuclear myopathy 1 (1); Encephalopathy (1); malaria (1); movement disorder (1); Parkinson disease (1); peripheral neuropathy (1); type 2 diabetes (1); vasculopathy (1).